SMIM23 (small integral membrane protein 23)
Synonyms: C5orf50; LOC644994
Tractability: Antibody: UniProt places it where antibodies can reach, with high confidence; UniProt predicts a signal peptide or a membrane-spanning region; its Gene Ontology location is reachable by antibodies, with medium confidence.
Gene: Protein-coding gene on chromosome 5 (171,782,432 to 171,796,126, forward strand). Ensembl gene ENSG00000185662.
Subcellular location: Cell membrane
Gene Ontology:
Cellular component: plasma membrane
Genetic constraint (gnomAD): Loss-of-function variants: 10 observed, 13.68 expected, observed/expected ratio (o/e) 0.73, 90% interval 0.45 to 1.24. The upper end of that interval is the gene's LOEUF score, 1.24, which puts it in group 5 of 6, group 1 being the genes least tolerant of losing a copy. Missense variants: 184 observed, 201.53 expected, observed/expected ratio (o/e) 0.91, 90% interval 0.81 to 1.03. Synonymous variants: 78 observed, 83.17 expected, observed/expected ratio (o/e) 0.94, 90% interval 0.78 to 1.13.
Homologues: Orthologues: chimpanzee SMIM23 (97% identical), macaque SMIM23 (73% identical), dog SMIM23 (68% identical), guinea pig SMIM23 (52% identical), rat Smim23 (51% identical), mouse Smim23 (48% identical).
Diseases named in the same sentence as SMIM23 in open-access papers:
SMIM23 is named in the same sentence as 1 disease in open-access papers, as found by Europe PMC text mining. Sharing a sentence is not in itself a finding about the gene and the disease.
SMIM23 shares sentences with these, for which no sentence is quoted: holoprosencephaly (1 paper).